ID1 (inhibitor of DNA binding 1)
Diseases named in the same sentence as ID1 in open-access papers (continued):
Sharing a sentence is not in itself a finding about the gene and the disease.
glioma (continued). "Given the recent reports that Id1 plays a significant role in maintaining glioma stem cells, we were interested in determining whether it would also do so in our tumor system." (PMID 24659686, 2014). "Recently, glioma-initiating cells (GICs) have been found to display high levels of Id1." (PMID 24659686, 2014). "Moreover, TGF-β inhibitors were found in an animal model to prevent glioma initiation and recurrence by reducing Id1 expression and depleting this GIC population." (PMID 24659686, 2014). "Thus, both COX-2 and Id1 expression also enhances tumorigenicity of glioma cells in an intracranial tumor model." (PMID 24659686, 2014). "Since we hypothesized that Id1 is a factor downstream of COX-2 enhancing its ability to alter transformation of glioma cells, we next assessed whether Id1 overexpression leads to increased soft agar colony formation." (PMID 24659686, 2014). "Actually, ID1 has been proposed as a marker of glioma-initiating cells." (PMID 23768125, 2013). "They suggest that CBD may act through modulation of Id-1, a transcription factor regulator that seems to be involved in glioma malignancy." (PMID 24204703, 2013). "Id1 has been shown to be expressed by adult neural stem cells and glioma stem cells." (PMID 23691228, 2013). "The present results therefore suggest that ID1-knockdown may inhibit U87 glioma cell proliferation and invasion." (PMID 24137437, 2013). "A very recent paper is providing new insights on the role of Id1, a transcriptional regulator of self-renewal in neural stem cells: high levels of Id1 could identify glioma stem cells." (PMID 22685459, 2012). "Transcriptome analysis revealed that silencing Id1 in microglia affected the expression of genes related to cell cycle and proliferation, while also uncovering a regulatory program involved in the expression of inflammatory genes, which was suppressed by glioma-derived factors." (PMID 37514199, 2023). "Similarly, other studies support the key role of ID1 in promoting glioma growth." (PMID 30279357, 2018). "Therefore, we became interested in testing whether overexpression of COX-2 results in Id1 expression in glioma cells." (PMID 24659686, 2014). "Therefore, we sought to determine whether COX-2 and Id1 overexpression will promote the migration and invasiveness of glioma cells." (PMID 24659686, 2014). "To assess whether Id1 enhances growth of glioma stem cells, we harvested flank tumors derived from LN229/Ctr and LN229/Id1 cells and made single cell suspensions that were then cultured in serum-free conditions designed to promote proliferation of neural stem cells within neurospheres." (PMID 24659686, 2014). "A transient upregulation for both Id1 and Id2 messengers was validated in BV2 microglia, 2 h post segregated coculture with C6 glioma cells, when compared to BV2 microglia monoculture." (PMID 39019900, 2024). "PTK7 regulates Id1 expression to promote cell proliferation and tumorigenesis, inhibit apoptosis of CD44-high gliomas, and induce anchorage-independent growth of normal astrocytes through the TGF-β/Smad signaling." (PMID 39474113, 2024). "TGF-beta supports the growth and survival of glioma cells; in glioma stem cells, TGF-beta induces the expression of its target ID1, whose biological activity contributes to self-renewal of these cells." (PMID 30279357, 2018). "In murine PDGFB-induced glioma cultures and primary human GBM cultures stroma-derived osteopontin was responsible for up-regulation of NANOG, SOX2, OCT4, and ID1 expression." (PMID 28030801, 2017). "TGF-β inhibition also reduces glioma stem-like cell (GSC) stemness via Leukaemia inhibitory factor (LIF), Sox4-Sox2, and inhibitor of DNA binding 1–3 (Id1–Id3)." (PMID 27743144, 2017). "TGFβ, Id1 and CD44 regulate glioma stem cells, which are responsible for glioblastoma initiation, relapse, and therapeutic resistance." (PMID 28122577, 2017).
glioma (continued). "ID1 plays a critical role in tumor maintenance of high-grade glioma (HGG), and deletion of ID1 and ID3 in vitro reduces invasiveness of HGG." (PMID 26662959, 2016). "After treatment with galunisertib, the expression of both ID1 and CD44 was reduced, suggesting that TGF-β signaling was inhibited in the glioma tissue." (PMID 25529192, 2015). "First, forced expression of COX-2 in two human glioma cell lines leads to elevated expression of Id1 and the COX-2 inhibitor CXB dramatically inhibits the expression of Id1 in COX-2-overexpressing LN229 cells." (PMID 24659686, 2014). "We have also identified a novel link between COX-2 and Id1 in gliomas and demonstrated that Id1 is a critical factor downstream of COX-2 required for enhancing the aggressiveness of glioma cells." (PMID 24659686, 2014). "In glioma-initiating cell, pivotal for cancer initiation and recurrence, the treatment of a TGF-β type 1 receptor inhibitor led to a reduction in the expression levels of ID1 and ID3." (PMID 38658527, 2024). "ID1 is well described in GBM progression, treatment resistance and glioma stem cell biology." (PMID 38127790, 2023). "In addition, TGM2 gene knockout inhibits the proliferation of glioma cells and reduces the expression of inhibitor of differentiation 1 (ID1), the downstream medium through which TGM2 regulates the proliferation of glioma cells." (PMID 37115802, 2023). "Although the status of EGFR was not analyzed, the effect of BMP4 on glioma cells was mediated by its downstream targets, p21CIP1 and ID1 (DNA-binding protein inhibitor 1)." (PMID 32788653, 2020). "High-grade glioma cells with high Id1 expression (but no Id2 and Id3 expression) show self-renewal capacity, whereas cells with low Id1 levels possess poor self-renewal capacity but proliferative potential." (PMID 28122577, 2017). "To evaluate if COX-2 overexpression affects transformation of human glioma cells, we first performed soft agar colony formation assay using SF767/control cells and two SF767/COX-2 clones (4L and 9) which express differing levels of both COX-2 and Id1." (PMID 24659686, 2014). "CBDis a well-tolerated, nonpsychoactive phytocannabinoid thatexhibits antitumor activity against GBM and glioma stem-like cells.This is achieved through mechanisms such as inducing oxidative stress,activating caspases, modulating ERK and TRPV2/TRPV4 signaling, andsuppressing NF-κB and Id1." (PMID 41288593, 2026). "Inhibitor of differentiation 1 (ID1), which has a helix-loop-helix structure that forms heterodimers with transcription factors, thereby inhibiting their function, has been shown to be highly expressed in GBM and identified as a key factor for maintaining features of glioma stem cells (GSCs)." (PMID 38658527, 2024). "However, the specific mechanism through which ID1 regulates these GBM cell properties requires further research, which may lead to the identification of new strategies and therapeutic targets for glioma treatment." (PMID 24137437, 2013). "Moreover, mouse survival significantly improves upon Olig2 but not Id1 deletion, suggesting that non-self-renewal glioma cells may have high impact on tumor growth." (PMID 28122577, 2017).
prostate carcinoma (40 papers, 2006 to 2024). A carcinoma that arises from epithelial cells of the prostate gland. "Beneficial effects of ID1 in CRC progression would also be in contrast to findings in prostate cancer, where increased expression was reported to be associated with poor survival of the patients." (PMID 34841646, 2022). "Together with Myc, increased Id1 expression is also associated with increasing grade of prostate cancer." (PMID 23786676, 2013). "Data presented in this study, from our previous studies, and as reported by others strongly suggest that Id1 is associated with prostate cancer." (PMID 23342268, 2012). "Of all the four Id proteins, the expression of Id1, Id2, and to a lesser extent, Id3 in prostate cancer and the underlying molecular mechanism is relatively well known." (PMID 23342267, 2012). "In conclusion, our results clearly demonstrate that Id1 and Id3 expression is associated with prostate cancer progression." (PMID 23342268, 2012). "Based on our and majority of studies, we can now confidently state that increased Id1 is associated with prostate cancer." (PMID 23342268, 2012). "We found that, in our prostate cancer patient cohort, high-level expression of Id-1 was associated with low TNF-β expression, which is consistent with our in vitro findings." (PMID 20010941, 2010). "Overexpression of Id1 is associated with progression of prostate cancer and Id1-induced androgen-independent prostate cancer cell growth is correlated with upregulation of EGFR." (PMID 20842131, 2010). "High-level expression of Id-1 was significantly associated with a low-level expression of TNF-β in the prostate cancer specimens (Fisher's exact test, P=0.03)." (PMID 20010941, 2010). "For example, in prostate cancer, patients with ID1 up-regulation were found to be associated with a significant delay in developing biochemical relapse and ID1 overexpression could sensitize cells to docetaxel-induced cytotoxicity." (PMID 30154433, 2018). "The results demonstrate that Id1 and Id3 expression is associated with prostate cancer." (PMID 23342268, 2012). "We propose that Id1 and Id3 together could have higher diagnostic and therapeutic value in prostate cancer." (PMID 23342268, 2012). "In addition, increased expression of Id-1 is significantly associated with shorter survival of prostate cancer patients." (PMID 20010941, 2010). "Previously, we found that stable overexpression of ID1 sensitizes prostate cancer cells to docetaxel chemotherapy by overwriting cell cycle checkpoints." (PMID 34820369, 2021). "ID protein inhibition by a peptide aptamer induces cell cycle arrest and apoptosis in ovarian cancer cells, and the inactivation of ID1 genes induces sensitivity of prostate cancer cells to chemotherapeutic drugs." (PMID 34295890, 2021). "Knocking out Id1 gene has an in-vivo preventive effect against the development of prostate cancer in mouse model." (PMID 32410828, 2020). "What's more, in the prostate cancer cell line LNCaP, docetaxel dose-dependently induced Id1 transcription and stable Id1 overexpression in LNCaP enhanced docetaxel-induced cytotoxicity." (PMID 32410828, 2020). "And a study involving 52 prostate cancer patients showed higher Id1 RNA expression predicted a higher hazard ratio for progression and a shorter disease-free survival." (PMID 32410828, 2020). "In contrast to the crucial role of Id1 in cancer, overexpression of its isoform in lung and prostate cancer cells leads to cell-growth arrest, tumor shrinkage, impaired angiogenesis and sensitization to radiotherapy-induced cell death." (PMID 28122577, 2017). "Curcumin significantly down-regulates mRNA and protein levels of Id1 in prostate cancer cells and xenografted tumors, which is accompanied by induction of apoptosis and tumor growth suppression." (PMID 28122577, 2017).
prostate carcinoma (continued). "In prostate cancer the over-expression of B-cell leukemia 3 (Bcl3) protein is correlated with the expression of Id1 and Id2, which is in turn accompanied with resistance to pro-apoptotic drugs." (PMID 28122577, 2017). "This was also seen in prostate cancer, where Id1 and Id3 were induced by TGFβ to inhibit proliferation." (PMID 26865052, 2016). "In prostate cancer cells, silencing Id1 induced the expression of the cell cycle regulatory proteins p16 and p21 and triggered a change in MMP-9 levels." (PMID 23517130, 2013). "We and others have shown that Id4 and Id1 expression is mutually exclusive in the normal prostate and prostate cancer." (PMID 23786676, 2013). "In other neoplasms, such as prostate cancer, the overexpression of Id1 has been also related to radioresistance." (PMID 23311395, 2013). "This study provides the first comprehensive analysis of Id1 and Id3 protein expression and localization in human prostate cancer." (PMID 23342268, 2012). "We have previously reported that silencing either Id1 or Id3 in prostate cancer cell lines LNCaP and DU145 cells independently attenuated proliferation." (PMID 23342268, 2012). "Id1 regulates prostate cancer (PCa) cell proliferation, apoptosis, and androgen independence, but its clinical significance in PCa remains controversial." (PMID 23342268, 2012). "Detailed cellular localization of Id1 and Id3 proteins in prostate cancer cell lines was investigated by immunocytochemistry (Id1 and Id3 expression shown in LNCaP and DU145 cells)." (PMID 23342268, 2012). "The purpose of this study was to investigate the expression and relevance of Id1 and Id3 proteins in prostate cancer." (PMID 23342268, 2012). "In spite of strong evidence supporting the role Id1 as a tumor promoter, its expression in prostate cancer is conflicting." (PMID 23342268, 2012). "Interestingly a stronger statistical association was observed in case of Id3 with prostate cancer as compared with Id1: the difference between Id3 expression in normal versus grade II was more significant in post hoc Dunn's multiple comparison test (***P < 0.001) as compared with Id1 (*P < 0.05)." (PMID 23342268, 2012). "Our results show that targeting Id3 alone can reduce prostate cancer cell proliferation significantly more as compared with silencing Id1 alone." (PMID 23342268, 2012). "We also demonstrate that Id3 alone blocked proliferation of prostate cancer cells as compared with Id1." (PMID 23342268, 2012). "The localization of Id1 and Id3 is also consistent with their localization in prostate cancer tissue." (PMID 23342268, 2012). "The cohort of modulated genes did not contain any cell cycle-associated genes, DNA-binding genes (e.g. RAD51) or transcriptional activation genes (e.g. Id-1) we have already reported in aggressive primary prostate cancers." (PMID 21799931, 2011). "We also analysed the expression levels of TNF-β using immunohistochemistry in 110 human prostate cancer specimens for which Id-1 expression status was already known." (PMID 20010941, 2010). "Id-1 promotes prostate cancer growth through inactivation of the p16/pRB pathway, and activation of the epidermal growth factor receptor and the MAPK pathway." (PMID 20010941, 2010). "In this study, we found that prostate cancer cells expressing different levels of Id-1 have both modulated levels of TNF-β and an ability to stimulate osteoblast mineralisation and osteoclast differentiation." (PMID 20010941, 2010). "This information suggests that Id-1 is important in both prostate cancer initiation and progression." (PMID 20010941, 2010). "Previously, we have shown that Id-1 expression in primary prostate cancer is correlated with Gleason score, and in a separate cohort we also showed that it is also correlated with mortality." (PMID 20010941, 2010). "Expressions of Id-1 and its downstream effectors in prostate cancers were studied using immunohistochemistry in a prostate cancer patient cohort (N=110)." (PMID 20010941, 2010).
prostate carcinoma (continued). "Conditioned media from prostate cancer cells, expressing various levels of Id-1, were used to stimulate pre-osteoclast differentiation and osteoblast mineralisation." (PMID 20010941, 2010). "In conclusion, Id-1 has already been shown to promote proliferation, invasion and survival of prostate cancer cells." (PMID 20010941, 2010). "Taken together, these results suggest that Id-1 has important roles in prostate cancer carcinogenesis and metastatic progression." (PMID 20010941, 2010). "In this study, we aimed to identify the role of Id-1 in prostate cancer to bone metastasis and its possible downstream targets by studying how bone cells respond to conditioned medium from prostate cancer cells expressing various levels of Id-1." (PMID 20010941, 2010). "In human specimens, Id-1 expression in prostate cancer is increased in comparison to benign prostatic hyperplasia specimens, and increased expression of Id-1 is correlated with Gleason score, reflecting the aggressive nature of Id-1-positive prostate cancers." (PMID 20010941, 2010). "Using lentiviral infection with shRNA, we established a stable clone of the osteolytic PC3 prostate cancer cell line (which endogenously expresses high levels of Id-1) that expressed low levels of Id-1." (PMID 20010941, 2010). "It has been reported that overexpression of Id-1 in prostate cancer cells play a role in angiogenesis whereby VEGF activation." (PMID 19014499, 2008). "Studies on prostate cancer, ovarian cancer and renal cell carcinoma showed high Id-1 levels to be correlated with high EGFR levels." (PMID 19014499, 2008). "Inhibitor of DNA-binding-1 expression was high in two androgen-independent prostate cancer cell lines, DU145 and PC3, but its expression is undetectable in the androgen-dependent cell line LNCaP under serum-free conditions." (PMID 19002177, 2008). "It has also been demonstrated that increased Id-1 levels are accompanied by high Gleason scores in prostate cancers." (PMID 19014499, 2008). "As prostate cancer progression and aggressiveness are judged by its response to androgen, these results support the role of ID-1 expression in tumour progression." (PMID 19002177, 2008). "Overexpression of Id-1 in prostate cancer cells also promotes metastasis through increased angiogenesis and invasiveness." (PMID 18000500, 2007). "Id-1 has also been shown to promote metastasis through increasing invasiveness and angiogenesis in breast and prostate cancer." (PMID 18000500, 2007). "BMP4 has also been shown to inhibit growth of the prostate cancer cell line LNCaP and induce the expression of ID1, ID2, and ID3 in cell lines." (PMID 16638148, 2006). "In prostate cancer, ID1 mediated docetaxel sensitivity via downregulating p21." (PMID 37964494, 2024). "This means the role of Id1 in prostate cancer is complicated and should be analyzed in specific." (PMID 32410828, 2020). "Moreover, γ-T3-induced apoptosis was also found to be associated with the suppression of NF-κB, epidermal growth factor receptor (EGFR), and Id family proteins (Id1 and Id3) in prostate cancer." (PMID 30866453, 2019). "Recently, Id-1 has been suggested as a potential oncogene, as aberrant elevation of Id-1 has been found in numerous types of cancers such as cervical, osteosarcoma and prostate cancers." (PMID 29233161, 2017). "Additionally, a previous study agreed with these conclusions revealing that Id-1 is able to protect anticancer drug induced apoptosis through activation of NF-κB pathways in prostate cancer." (PMID 29233161, 2017). "Caveolin-1, a cell membrane protein and positive regulator of cell survival and metastasis in prostate cancer, may interact with the helix-loop-helix domain of Id1." (PMID 28122577, 2017). "ID1 has been suggested as a potential oncogene, because it was found to be up-regulated in many types of human cancer such as breast, pancreas, kidney, and prostate cancers." (PMID 29169374, 2017).